MIR495 (microRNA 495)
Synonyms: hsa-mir-495; MIRN495; mir-495
Gene: MicroRNA gene on chromosome 14 (101,033,755 to 101,033,836, forward strand). Ensembl gene ENSG00000207743.
Gene Ontology:
Biological process: miRNA-mediated post-transcriptional gene silencing
Cellular component: RISC complex
Homologues: Orthologues: chimpanzee ptr-mir-495 (100% identical).